IL6 (interleukin 6)
Diseases named in the same sentence as IL6 in open-access papers (continued):
Sharing a sentence is not in itself a finding about the gene and the disease.
depression (continued). "Moreover, despite a tendency to an increase in plasma, IL-6 mRNA levels were found downregulated in the PBMCs of depression patients, in what we hypothesize could be a mechanism of negative feedback, to compensate the increased levels of IL-6 and other dysregulated cytokines in plasma." (PMID 37575572, 2023). "Our present results showed that long-term EE effectively decreased the expression levels of IL-1β, IL-6, and TNF-α, and improved depression and cognitive deficits in the MSD + EE group compared with those of the MSD group." (PMID 37168717, 2023). "Ketamine, a novel rapid-acting antidepressant, reduces serum and cerebrospinal fluid IL-6, and serum IL-1β and TNF-α, while treating depression." (PMID 36838809, 2023). "Higher levels of IL-6, NLRP3, and TNF- α predicted a better response to ECT in patients with treatment-resistant depression." (PMID 37699900, 2023). "Also, another study showed that the level of interleukin 6 in women having positive social relationships and a purpose for life is lower compared with other women, suggesting that people experiencing anxiety, depression and anxiety have a higher level of interleukins in their bodies." (PMID 37692307, 2023). "In the current study, a positive correlation was found between TNF-α, IL-6, IL-8, and IL-17A after AIS onset and anxiety, depression, or cognitive impairment at different time points." (PMID 37878890, 2023). "Serum IL-6, IL-8, IL-18, and IFN-γ are estimated biomarkers for depression and can identify the physiopathology of inflammatory regulation abnormalities in depression." (PMID 37637801, 2023). "First, pro-inflammatory cytokines such as IL-6 and TNF impair the expression of BDNF, leading to the onset of depression." (PMID 36978923, 2023). "For example, long-term corticosterone treatment significantly increased the mRNA levels of IL-1β, IL-6, and TNF-α in the hippocampus and hypothalamus, which in turn increased the anxiety-and depression-like behaviors in mice." (PMID 37168717, 2023). "The results revealed that depression patients’ plasma levels of CCL2, IL-6, IL-4 and IL-10 were all positively correlated." (PMID 37575572, 2023). "Several studies have shown that the intraperitoneal injection of LPS upregulates the expression of proinflammatory cytokines, including IL-1β, IL-6, and TNF-α, leading to anxiety, depression, and cognitive deficits." (PMID 37560531, 2023). "Antidepressant agomelatine (AGO) eliminated depression in HFD rats, reduced the activity of inflammatory cytokines (TNF-α, IL-6, and IL-1β), TABRS, and restored the activity of CAT and GPX." (PMID 37108261, 2023). "Moreover, this significant increase in cytokines, especially interleukin 6 (IL-6), which penetrates the blood–brain barrier (BBB), appears to alter neuronal functions and cause complications in the central nervous system (CNS), dysautonomia, depression, and hearing loss." (PMID 37894116, 2023). "Cortisol and IL-6 are important in the pathogenesis and maintenance of both T2DM and depression (a state of extreme limbic system inhibition)." (PMID 37664841, 2023). "Participants were evaluated for depressive symptoms using the Beck Depression Inventory-II (BDI-II) and had blood work quantifying IL-6 and CRP at baseline and during follow-up visits." (PMID 38299049, 2023). "In particular, it was shown that the levels of some inflammatory cytokines (i.e., IL-6, IL-1, TNF-α, etc.)were significantly increased in the serum of MDD patients and in the brain of rodent models of depression." (PMID 37298063, 2023). "Researchers have observed high levels of pro-inflammatory cytokines including interleukin-1β (IL-1β), IL-6, and tumor necrosis factor-α (TNF-α) in the blood of patients suffering from depression and anxiety." (PMID 35242039, 2022).
depression (continued). "A study on the role of neurodevelopment and genes in psychiatric comorbidity and the regulation of inflammatory process in AD revealed that St8sia2 was only associated with the existence of clinical depression, rather than with AD, and St8sia2 could regulate inflammatory factors (IL-6, IL-1β, etc.)." (PMID 36279395, 2022). "Increases in IL-6 and TNF-α levels in CSF and brain parenchyma are considered markers of central inflammation in depression in the context of a possible increased microglia activity and reduction of astrocyte and oligodendrocyte markers." (PMID 36142325, 2022). "Microglia activation, increased IL-6 and decreased TGF-β were found in depressed patients or in animal models of depression." (PMID 36430328, 2022). "The concentrations of depression-related factors (5-HT and DA) and inflammatory factors (TNF-α, IL-6, and IL-1β) in the hippocampus and serum were assessed by ELISA assay." (PMID 36506556, 2022). "In this research, relatively stable markers, such as IL-6 and TNF-α, demonstrated enhanced and robust performance in predicting depression in patients with glioma." (PMID 35757220, 2022). "Corroborating this observation, higher concentrations of proinflammatory cytokines, such as IL-6 and TNF-alpha, are observed more often in patients with depression than in healthy subjects." (PMID 35237160, 2022). "Increase in inflammatory cytokines (IL-1β, IL-6, and TNF-α) has also be reported in common neuropsychiatric conditions including depression and schizophrenia." (PMID 35538558, 2022). "Elevated IL-1β, IL-6, TNF-α and IL-17 levels were observed in clinical patients with pain and depression comorbidity." (PMID 35733107, 2022). "Proinflammatory cytokines, including interleukin-6 (IL-6) and tumor necrosis factor-alpha (TNF-α), have been found to be higher in patients with major depressive disorder, while their antioxidant capacity is lower." (PMID 36339940, 2022). "Serum 25(OH)D, intact parathyroid hormone (iPTH), interlukin (IL)-1β, IL-6, high-sensitivity C-reactive protein (hs-CRP) and depression severity (Beck Depression Inventory-II) (BDI-II)) were initially and finally assessed." (PMID 36368945, 2022). "Not only pro-inflammatory cytokines (e.g., IL-1β and TNF-α) were found to be dysregulated in depression patients, but also IL-1β, IL-6, TNF-α, or lipopolysaccharide (LPS) administration in animal models led to depression- and anxiety-like behaviours." (PMID 36145259, 2022). "For example, intravenous or subcutaneous IL-1β injection increased depression-like behavior in mice and enhanced the expression of pro-inflammatory cytokines TNF-α and IL-6 in the amygdala, which is regulated by the CORT/GR system." (PMID 36232376, 2022). "In animal models of depression, IL-6 was reduced in the CA1 region of the hippocampus of rats exhibiting depressive behaviors and IL-6 knockdown facilitated development of depressive behaviors." (PMID 36614020, 2022). "The levels of neuropeptide Y (NPY), testosterone (T), and IL-1β, IL-6, TNF-α, IL-10, and IL-4 in the peripheral blood plasma of normal people, patients with depression, and patients with DCMI were measured." (PMID 35432561, 2022). "In a meta-analysis studying inflammatory markers in depression (collecting 5166 patients with depression and 5083 healthy controls), the researchers found that IL-6, TNF-α, IL-12, IL-3, IL-18, and sIL-2R were elevated in depression group." (PMID 36408212, 2022). "FA and serum cytokines (IL-1β, IL-6, TNF-α, and IFN-γ) were measured in 25 patients with depression (DE) and 24 healthy controls (HC)." (PMID 36261698, 2022). "Our results revealed that the administration of conventional coffee and decaffeinated coffee ameliorated depression-like behaviors in rats of PSD induced, as well as the changed levels of IL-6, TNF-α, SOD, and GSH-Px." (PMID 35283829, 2022).
depression (continued). "The AGE-RAGE signaling pathway mediates NF-kB activation and upregulates the expression of proinflammatory cytokines (e.g., IL-1β, IL-6 and TNFα) and growth factors (e.g., VEGF), which contribute to depression development and progression." (PMID 35626632, 2022). "With significantly improved depression symptoms, the post-treatment hs-CRP, TNF-α, and IL-6 levels in the drug naïve patients with MDD were lower than that in the HC." (PMID 35911989, 2022). "A recent metanalysis reported an increase in systemic pro-inflammatory cytokines, IL-1, IL-6, TNF-alpha and C-reactive protein (CRP) in depression patients." (PMID 35323251, 2022). "In similar studies, patients with depression were found to have elevated levels of proinflammatory cytokines, including tumor necrosis factor-α (TNF-α), interleukin 1β (IL-1β), IL-6, and C-reactive protein (CRP)." (PMID 35054853, 2022). "Studies have shown that the levels of pro-inflammatory cytokines such as interleukin-6 (IL-6) and tumor necrosis factor (TNF) in patients with depression are significantly increased." (PMID 36297505, 2022). "A meta-analysis of 24 studies in depressed patients found that individuals with major depression had significantly higher TNF-α and IL-6 plasma concentrations in comparison to controls." (PMID 35267893, 2022). "For instance, in colorectal cancer patients, serum IL‐1β, IL‐6, interleukin‐8 (IL‐8), and TNF‐α are positively correlated with increased anxiety and depression." (PMID 34697903, 2022). "Classical monocytes lead to ischemic lesions by producing IL-1β, IL-6, and TNF-α, which are connected with the presence of depression." (PMID 35935403, 2022). "Given epidemiologic relationships identified between IL-6, tumor necrosis factor (TNF)- α, and subsequent depression, levels of these pro-inflammatory cytokines were also explored as potential moderators of depressed mood response to endotoxin." (PMID 35871638, 2022). "ACE inhibitors can, therefore, effectively reduce inflammatory mediators, such as IL-6 and CRP, and play a role in improving depression, anxiety, and other adverse emotions." (PMID 35527821, 2022). "Research shows the presence of an increase in IL-6 and TNF-α levels in major depressive disorder (MDD) patients cerebrospinal fluid (CSF), and brain parenchyma, in the context of a possible increased microglial reaction." (PMID 35370734, 2022). "In BD depression, IL-6 is the predominant cytokine, in euthymic state it is IL-4, and in manic episode it is IL-2, IL-4, IL-6, while patients with unipolar depression have mainly elevated TNF-α, IL-6 and soluble IL-2 receptor (sIL-2R)." (PMID 36294388, 2022). "Patients with depression often have elevated TNF-α, IL-1, IL-1β, IL-2, IL-6, IL-8, IL-17, IL-21, IL-23, C-reactive protein, and TGF-β." (PMID 35054853, 2022). "Serum IL-6, IL-17, and CRP were measured before and after selective serotonin reuptake inhibitor (SSRI) therapy, as well as Hamilton rating scale for depression (HAMD) and life event scale (LES) scores." (PMID 35615531, 2022). "This indicates that the concurrent elevation of IL-6 and TNF-α should be highly suspected of depression, while meanwhile, reminding the clinical staff to carefully observe and timely formulate innovative therapeutic strategies." (PMID 35757220, 2022). "Of note, some meta-analyses established that cytokines, including IL-6, IL-10, TNF-α and MCP-1, were found increased in patients with depression compared with healthy controls." (PMID 36139563, 2022). "Enormous studies have manifested increased levels of proinflammatory cytokines such as CRP, IL-1β, IL-6, and TNF-α in elderly patients with depression (and the patients underwent surgery)." (PMID 35356751, 2022). "A correlation was also observed between depression and CRP, IL-6, and IL-1ra in CTQ+ participants; perceived stress also links up with CRP and IL-6." (PMID 36231913, 2022).
depression (continued). "The Young Manic Rating Scale (YMRS), Self-Rating Depression Scale (SDS), and Interleukin-6 (IL-6), Tumor necrosis factor-α (TNF-α) and C-reactive protein (CRP) levels will also be measured." (PMID 36458119, 2022). "This meta-analysis included 22 eligible studies of 827 patients with major depressive disorder (MDD): seven studies for IL-1β, 15 for IL-6, 11 for TNF-α, six for IL-4, and four for interferon-γ." (PMID 35280153, 2022). "The study demonstrated that imbalances between IL-6 and TGF-β and between Th17and Treg occurred in the hippocampus of the depression model." (PMID 36430328, 2022). "Antidepressants influence unfavorable immune phenomena in depression, reducing the level of pro-inflammatory cytokines (e.g., TNF-α, IL-6), which are also pain mediators." (PMID 35955097, 2022). "Th17 cells participate in depression, which is activated by several cytokines, such as IL-1β, TNF-α, and IL-6." (PMID 35054853, 2022). "A study revealed that the levels of interleukin-6 (IL-6), tumor necrosis factor-alpha (TNF-α), and interleukin-8 (IL-8) were increased in cerebrospinal fluid (CSF) of patients with depression." (PMID 36844911, 2022). "IDO1, a therapeutic target in depression, metabolizes tryptophan to KYN and is upregulated during pro-inflammatory states induced by several cytokines (IL-1β, IL-6, IFN-α, TNF-α)." (PMID 35501309, 2022). "As was revealed in several experiments in animal models of depression, quercetin exerted antioxidant (reducing ROS, increasing SOD, GST, GSH activity) as well as anti-inflammatory activity (suppressing IL-1β, IL-6, TNF-α, COX-2, microglial activation)." (PMID 35455082, 2022). "Strikingly, upregulated levels of IL-6 and TNF-α in serum of patients with depression or Alzheimer’s disease were identified, suggesting a role of pro-inflammatory cytokines in promoting cognitive disorders." (PMID 36061856, 2022). "It is believed that even psychosocial factors and bitter events of life, first cause an increase in pro-inflammatory biomarkers such as IL-1β, IL-6 and hs-CRP which is then followed by depression." (PMID 36368945, 2022). "Corresponding with this, in this study, the IL-6 levels at the time of AMI were significantly and positively correlated with the Hamilton rating scale for depression (HAMD-17) scores 6 months after AMI." (PMID 36358455, 2022). "In the same study, IL-6, TNF-α, IL-17a and IL-12p70 were elevated in the depression group on the third day after AMI compared to the control group." (PMID 36358455, 2022). "The levels of IL-4, IL-10, T, and NPY in depression patients, DCMI patients, and CUMS + LPS model rats elevated, while the levels of IL-1β, IL-6, and TNF-α were reduced." (PMID 35432561, 2022). "A meta-analysis of the mean differences and variability in 5166 patients and 5083 controls showed that the levels of CRP, IL-3, IL-6, IL-12, IL-18, sIL-2R, and TNF-α were significantly higher in patients with depression." (PMID 35409300, 2022). "In particular, IL-1β, IL-2, IL-6, TNF-α and IFN-γ are reported to be involved in cytokine-induced depression." (PMID 36045388, 2022). "Among inflammatory markers, elevated levels of C-reactive protein, IL-6, and TNF are the most reliable markers of depression." (PMID 36619667, 2022). "Proinflammatory cytokines, including interleukin (IL)-6 (area under the curve (AUC) = 0.76) and tumor necrosis factor (TNF)-α (AUC = 0.75), showed good performance in accurately predicting depression in patients with glioma." (PMID 35757220, 2022). "A similar coupling of depression with elevated CRP and IL-6 has also been found among female adolescents who had experienced childhood adversity." (PMID 34990745, 2022). "In a meta-analysis that compared 5166 patients with depression and 5083 controls, patients with depression exhibited a significantly higher pro-inflammatory state (i.e., higher levels in CRP, L-3, IL-6, IL-12, IL-18, sIL-2R, and TNFα) than controls." (PMID 35682203, 2022).
depression (continued). "In the present study, we discovered that high TNF-α and IL-6 were correlated with cognition impairment occurrence; high TNF-α, IL-1β, and IL-17 were correlated with anxiety or depression occurrence in AIS patients." (PMID 35239774, 2022). "The M1 state of microglia is characterized by the elevated secretion of proinflammatory cytokines, including IL-1β, IL-6, and TNF-α, which trigger neuronal damage and contribute to the development of anxiety and depression." (PMID 35209199, 2022). "In the current study, eight weeks supplementation with vitamin D was not able to significantly change serum concentrations of pro-inflammatory biomarkers including IL-1β, IL-6 and hs-CRP in the subjects with mild to moderate depression." (PMID 36368945, 2022). "According to previous findings, interleukin-6 elevates STAT3 levels and promotes depression by increasing serotonin transporters (SERT)." (PMID 35164154, 2022). "Inflammatory cytokines (IL-6 and TNF-α), inflammatory diet (Diet Inflammatory Index; DII), and depressive symptoms (Beck Depression Inventory-II; BDI-II) were measured in 136 females (Mage = 22.01 ± 4.02, range 18–59 years)." (PMID 35651828, 2022). "Therefore, IL-6 may contribute to BC and depression in comorbid states." (PMID 36364213, 2022). "The results of some previous observational studies showed an inverse association between circulating concentrations of inflammatory mediators (IL-6 and hs-CRP) and 25(OH)D in subjects with depression." (PMID 36368945, 2022). "In conclusion, this study provides support that both IL-6 and TNF-α are related to a meta-analysis derived somatic dimension of depression." (PMID 35651828, 2022). "The Dietary Inflammatory Index (DII), validated in previous depression studies, correlates with elevated inflammatory markers such as CRP, IL-6 and TNF-α." (PMID 35172770, 2022). "NAC also exerts an anti-inflammatory role by decreasing various cytokines in the brain, especially IL-6, TNF-α and IL-1β, which are involved in the inflammatory mechanisms of depression." (PMID 36291336, 2022). "One meta-analysis suggested that the levels of some cytokines, such as IL-6, IL-12, and TNF-α, are higher in patients with depression." (PMID 35887634, 2022). "Prior evidence suggests that inflammatory cytokines (such as IL‐1β, IL‐6, and TNF‐α) are related to anxiety and depression in cancers, including colorectal cancer, breast cancer, and pancreatic cancer." (PMID 34697903, 2022). "The most significant changes were found for two pro-inflammatory factors: IL-6 and CRP, which were increased in patients with depression compared to healthy controls." (PMID 35163141, 2022). "The primary aim of this study was to compare the CSF levels of IL-6, IL-8 and TNF-α in geriatric patients with depressive disorders and an age- and sex matched control group." (PMID 36172507, 2022). "The findings in this study do not support a role of CNS inflammation, as measured by altered CSF levels of IL-6, IL-8, TNF-α, IL-10, MCP-1 or TGF β, in geriatric patients with depressive disorders." (PMID 36172507, 2022). "Clinical evidence showed that inflammatory mediators were elevated in patients with depressive disorder, such as HMGB1, IL‐1β, TNF‐α, CRP, IL‐6, and so on." (PMID 35089644, 2022). "Research has demonstrated positive correlations between cytokines interleukin (IL)-6 and tumor necrosis factor (TNF)-α and symptoms of depression in meta-analyses of both community samples and adults diagnosed with major depressive disorder (MDD)." (PMID 35651828, 2022). "Specifically, in this geriatric patient sample, we were not able to replicate previous findings of elevated CSF levels of inflammatory markers IL-6, IL-8 and TNF-α in patients with depressive disorders." (PMID 36172507, 2022). "UCMS induced anhedonia and hopeless behavior in mice, and changed expression levels of the depression-related genes BDNF, CREB, GR, SGK1, FKBP5, IL-1β, IL-6, and TNF-α in the frontal cortex and hippocampus." (PMID 34358084, 2021).